FASLG (Fas ligand)
Diseases named in the same sentence as FASLG in open-access papers (continued):
Sharing a sentence is not in itself a finding about the gene and the disease.
tumor (continued). "Fas-ligand (FasL), a member of the tumor necrosis superfamily, plays a central role in the induction of the apoptotic effect of CD8+ T cells and NK cells against cancer cells." (PMID 31098389, 2018). "It represses CTL-mediated tumor cytotoxicity by altering the expression of perforin, granzyme A, granzyme B, Fas ligand (FASL), and IFNγ." (PMID 29486723, 2018). "For instance, our team recently described that the infiltration of T cells into the tumor endothelial barrier was mediated by the death mediator Fas ligand (FasL/CD95L) in the tumor vasculature of human and mouse solid tumors." (PMID 30477198, 2018). "Studies indicated that the expression of the death Fas ligand (FasL/CD95L) was exclusively expressed in tumor vasculature and created a barrier that suppressed normal T cell function, allowing tumor cells to grow unrecognized by the immune system." (PMID 29854318, 2018). "Reduced FAS expression and/or increased FASLG expression facilitate tumor development and progression by inhibiting tumor cell apoptosis or by inducing immune cell apoptosis." (PMID 29950587, 2018). "Tregs were shown to inhibit Fas ligand-induced innate and adaptive tumor immunity in similar model and their removal improved tumor rejection." (PMID 28623375, 2018). "The combination of radiation and tumour-specific vaccines has been shown to increase anti-tumour immune responses in an animal model, possibly due to the upregulation of Fas ligand on tumour cells." (PMID 30577459, 2018). "Fas-ligand (FASLG), an upstream activator of pro-apoptotic signalling through Caspase 8 is also upregulated in the immune hot tumours, further highlighting the importance of this pathway." (PMID 30104673, 2018). "In fact, induction of T cells apoptosis by tumor-derived exosomes occurs through receptor-mediated pathways involving Fas Ligand (FasL), TRAIL, and PDL-1." (PMID 29515996, 2018). "Alternatively, increased in vitro endothelial cell presentation of Fas (CD95) was observed with >1 nM concentrations of docetaxel, and ABT-510-dependent apoptosis of tumor endothelial cells was shown to be induced by their upregulation of Fas ligand (CD178)." (PMID 28976305, 2017). "OK-432 upregulated the expression of CD56 and cell surface TRAIL and Fas ligand on mIFN-DCs, and the independent involvement of TRAIL and Fas ligand in mIFN-DC-mediated tumour killing was proven via specific antibody blockade." (PMID 28191816, 2017). "TGF-β inhibits T cell-mediated tumor clearance in vivo by specifically inhibiting the expression of five cytolytic gene products, including perforin, granzyme A, granzyme B, Fas ligand, and IFN-γ, in CTLs30." (PMID 28687760, 2017). "Resveratrol prompts the death of tumor cells by modulating diverse signal transduction pathways via regulation of the levels of Fas and Fas-ligand (FasL)." (PMID 29194365, 2017). "NK cells also expression Fas ligand (FasL), which binds and activates death receptor Fas on tumor cells and induces apoptosis." (PMID 28861089, 2017). "Type-I NKT cells can directly destroy tumor cells, especially those expressing CD1d on their surface, by performing cytolysis via perforin, granzyme B, Fas ligand (FasL), and TRAIL." (PMID 29354122, 2017). "Blocking Fas-ligand increases the anti-tumor efficacy of adoptive T-cell therapy in TiRP tumors, and increases the efficacy of checkpoint blockade in transplanted tumors." (PMID 29123081, 2017). "Bone marrow endothelial cells cultured with these cytokines and conditioned media were assessed for similarity to tumor endothelium by quantification of expression of Fas ligand, TEM-1, and ability to induce apoptosis in PHA activated splenocytes." (PMID 28404894, 2017). "The Fas/Fas ligand (Fas/FasL) pathway plays a significant role in tumorigenesis, and its impairment in cancer cells leads to apoptotic resistance and contributes to tumor progression." (PMID 28353631, 2017).
tumor (continued). "In fact, in the model of Fas-ligand-induced inflammation in which injecting FasL-expressing tumor cells into peritoneum of mice induces enhanced production of IL-17 from non-conventional T cells." (PMID 26858718, 2016). "Peripheral and tumor-associated NK cells from STAT3-targeted tumor-bearing mice also expressed elevated levels of NK activation markers NKG2D, CD69, and Fas ligand (FasL)." (PMID 27148255, 2016). "During cancer progression, the interaction between Fas and Fas-ligand (FasL) is largely impaired due to suppression of Fas expression on tumor cells." (PMID 27978543, 2016). "The results indicated that let-7c was a key miRNA which regulated 3 tumor toxic molecules including Fas ligand (FasL), TNFSF10 (Trail) and OSM (Oncostatin M)." (PMID 25826780, 2015). "Tumor-specific CD4+ and CD8+ T cells migrate to the tumor site, and CTLs induce cell lysis and/or apoptosis in antigen-bearing tumor cells through the release of perforin and granzymes or by a Fas/Fas ligand interaction." (PMID 25756279, 2015). "The tumor endothelium is also prohibitive to entry of tumor-reactive T lymphocytes by suppression or direct killing of effector T cells via molecules such as Fas ligand (FasL)." (PMID 26510973, 2015). "Ectopic Fas-ligand (FasL) expression in tumor cells is responsible for both tumor escape through tumor counterattack of Fas-positive infiltrating lymphocytes and tumor rejection though inflammatory and immune responses." (PMID 26236689, 2015). "In a model of Id-specific CD4+ T cell responses against an MHC IIPOS B lymphoma, in vitro cytotoxicity was shown to be dependent on signaling mediated by binding of Fas ligand (FasL) on CD4+ T cells to the death receptor Fas on tumor cells." (PMID 24782871, 2014). "Fas ligand and TNFα reportedly kill not only tumor cells but also normal cells, whereas, TRAIL is promising because of its high selectively to cancer cells." (PMID 24297392, 2014). "Humans have several defence mechanisms to prevent tumor progression, with the Fas/Fas ligand (Fas/FasL) system being one of the major and best-known mechanisms for evading tumor cells." (PMID 29147372, 2014). "Sub-lethal doses of irradiation in a mouse adenocarcinoma model increased the anti-tumor activity of ACT Ag-specific cytotoxic T cells by utilizing the Fas/Fas ligand pathway of tumor death." (PMID 25566495, 2014). "Oleandrin induces cell death through the activation of caspases in a variety of human tumour cells, as well as by activating calcineurin and NF-AT via the Fas ligand." (PMID 23521834, 2013). "Exosome-mediated transfer of Fas ligand from tumor cells induces apoptosis of activated T cells enabling tumor immune escape." (PMID 23908664, 2013). "Fas ligand (FasL or death factor) is expressed mainly in cytotoxic T lymphocytes, immune privileged sites, and in various tumours." (PMID 23152729, 2012). "An attractive insight into mechanism of tumor escape from immune clearance has been provided by the identification of the “Death factors”, including Fas/Fas Ligand (Fas/FasL) as an important regulator of both apoptosis and immune function." (PMID 23300494, 2012). "Prior to the discovery of TRAIL, two other members of the TNF family—the prototypic TNF and the closely related Fas Ligand (FasL)—had been identified as potent inducers of tumor cell death." (PMID 24212631, 2011). "Signaling by Tumor Necrosis Factor-Related Apoptosis Inducing Ligand (TRAIL) and Fas ligand (FasL) has been proposed to contribute to the chemosensitivity of tumor cells treated with various other anti-cancer agents." (PMID 21264287, 2011). "Of note, both tumor cell lines also expressed high levels of Fas which is recognized to establish cell death upon interaction with its ligand, Fas-ligand." (PMID 20937115, 2010).
tumor (continued). "The Fas ligand (FasL) can induce apoptosis in the target cell expressing the Fas receptor, while both ligand and receptor are expressed on tumor cells and T-cells at different levels depending on developmental state." (PMID 21234354, 2010). "Accordingly, given the expression of Fas ligand on a variety of tumors, we and others have sought, and successfully demonstrated that FasL is expressed on exosomes secreted by tumor cells." (PMID 18644158, 2008). "By comparison, other authors found Fas-ligand dependent mechanisms or an inhibition of tumor angiogenesis to be responsible for the inhibition of tumor growth." (PMID 19077262, 2008). "It has also been reported that HNF4α is downregulated in other types of tumours and that it induces expression of endothelial Fas ligand (FasL), which prevents cancer cell transmigration." (PMID 16479257, 2006). "Fas ligand expression was present more frequently in G1-2 than in G3 tumours (P<0.0001), and tended to be more frequent in Ta-1 than T2-4 (P=0.061)." (PMID 16091761, 2005). "Human mesothelial cells and SW480 tumour cells constitutively expressed Fas and Fas Ligand mRNA and protein as determined by RT–PCR and confocal fluorescent microscopy." (PMID 15054468, 2004). "Recent studies have identified an additional mechanism of tumour immune evasion involving expression of the apoptosis-inducing protein Fas ligand (FasL/CD95L)." (PMID 14520470, 2003). "Among the candidate apoptotic signals, the Fas (also named as CD95, APO-1)/Fas-ligand (Fas-L) system plays important roles in organ homeostasis and immune surveillance against tumours." (PMID 12177809, 2002). "Additionally, B cells can function as antigen-presenting cells, secrete various cytokines, and exert direct cytotoxic effects through Fas ligand (FasL) expression, including against tumor cells." (PMID 40861439, 2025). "The surfaces of exosomes derived from tumor cells contain tumor-specific protein molecules, including Fas ligand (FasL), tumor necrosis factor-related apoptosis-inducing ligand (TRAIL), transforming growth factor-β (TGF-β) tumor antigens, and immunosuppressive proteins 50,51." (PMID 39744442, 2025). "Another study revealed that direct cell contact between Fas ligand (FasL) on human neutrophils and Fas on tumor cells could inhibit the cell cycle of tumor cells in vitro." (PMID 39653768, 2025). "Malignant T cells may also inhibit anti-tumor immunity by inducing apoptosis in reactive T cells, through Fas ligand (FasL) expression]." (PMID 41171472, 2025). "Furthermore, NKs can release cytokines like IFN-γ and perforin/granzyme, and express TNF-related apoptosis-inducing ligand (TRAIL) and Fas Ligand (FasL) to activate apoptotic pathways in tumor cells." (PMID 40008144, 2025). "In addition, the Fas ligand (FasL) on CTLs binds Fas receptors on tumor cells, triggering caspase-mediated apoptosis." (PMID 40565031, 2025). "Moreover, tumor and stromal cells in hypoxic regions upregulate PD-L1, Fas ligand (FasL), and galectin-9, which engage death receptors on T cells (e.g., PD-1, Fas, TIM-3) to initiate extrinsic apoptosis." (PMID 40963621, 2025). "However, in tumors, FASLG can paradoxically promote immune evasion and tumor growth by inducing apoptosis in immune cells or through non-apoptotic signaling pathways, illustrating its dual role in cancer." (PMID 40665092, 2025). "Importantly, MSC-sourced IL-15 not only enhances viability and expansion of NK cells, but also up-regulates expression of cytotoxic molecules (perforin, granzyme B, and Fas ligand (FasL)), thereby augmenting their ability to directly kill tumor cells." (PMID 40643499, 2025). "Tumor NK cells downregulated canonical NK activation markers, such as FASLG, TNFSF10, KLRK1, GZMB, and KLRD1, the latter having both inhibitory and activator capabilities but being a marker of favorable prognosis in human cancers if present in either the serum or tumor." (PMID 41208961, 2025).
tumor (continued). "In addition, the IFN-γ/Stat1 signaling pathway induces genes such as caspase-1 and Fas and Fas ligand (FasL), which promote tumor cell apoptosis." (PMID 40722781, 2025). "Additionally, evidence supports the involvement of Fas/Fas Ligand (FasL) interplay in immune evasion, with neoplasms showing resistance to Fas-mediated cytotoxicity and FasL expression potentially resulting in immune effector cells apoptosis." (PMID 38893120, 2024). "One such pathway through which neutrophils may trigger tumor cell death is the Fas–Fas ligand (FasL) pathway." (PMID 38474175, 2024). "For example, Fas ligand (Fas‐L) and perforin can induce tumor cell apoptosis." (PMID 39229670, 2024). "Additionally, TEXs expressing Fas ligand, a molecule capable of inducing T-cell apoptosis, have been found to suppress T-cell responses and promote tumor immune evasion." (PMID 38920249, 2024). "Finally, upregulation of the Fas ligand (FasL) in NK cells induces apoptosis in Fas‐expressing tumor cells through the Fas‐FasL pathway, a key death factor in NK cell antitumor activity." (PMID 38270321, 2024). "The FAS ligand (FASL) pathway is another crucial pathway, which is cytotoxic for tumor cells." (PMID 39072335, 2024). "As higher antigen levels have been correlated with more perforin/granzyme activity in CD8+ T cells, we assume that cytotoxic T lymphocytes (CTLs) employ perforin/granzyme to eliminate high antigen tumor cells but resort to Fas ligand (FasL) for the elimination of low antigen tumor cells." (PMID 38515743, 2024). "Consequently, CD8+ T cells are activated to kill tumor cells via the granzyme, perforin, and Fas/FasL (Fas ligand) pathways." (PMID 39195299, 2024). "On the other hand, VEGF inhibits the adhesion of lymphocytes to endothelial cells through intercellular adhesion molecule-1 (ICAM-1), vascular cell adhesion molecule-1 (VCAM-1), and Fas Ligand (FasL), thereby affecting the infiltration of T cells into the tumor tissue." (PMID 36936932, 2023). "In other words, death receptor-mediated apoptosis signals are more sensitive to the control of anoikis than Fak-mediated survival signals, which can explain why the loss of anchoring leads to an increase in Fas expression and Fas-ligand (Fas-L) expression during the anoikis of tumor cells." (PMID 37667281, 2023). "Additionally, multiplex assays also revealed increased cytokine production and cytotoxicity driven by granzymes and soluble Fas ligand (sFasL), suggesting enhanced anti-tumor immune responses." (PMID 37894816, 2023). "In addition, tumor ECs can express PD-L1 and Fas ligand to inhibit T cell activation and induce apoptosis of immune effector cells, respectively, leading to an immunosuppressive TME." (PMID 36901858, 2023). "Cytotoxic T cells also promote tumor cell death through Fas-FASL (Fas ligand) interactions." (PMID 37759777, 2023). "Moreover, PD-1-containing EVs also directly attacked tumor cells via Fas-ligand (FasL) and granzyme B (GzmB)." (PMID 37686050, 2023). "Outcomes included immunohistochemistry of dendritic cells (DCs), M1 and M2 macrophages, T-helper cells (Th1) (CD4+), cytotoxic T- lymphocytes (CTL) (CD8+), T-regulator cells (T-reg) (FoxP3+) and Fas Ligand activated CTLs (Fas-L+) in the periablational rim and untreated index tumor." (PMID 37883367, 2023). "However, a dual role of FASLG has been proposed, where cells in the tumor milieu can express FASLG to facilitate immune escape by engaging the Fas receptor on T cells leading to the apoptosis of T cells." (PMID 38067332, 2023). "Administration of a peptide vaccine functionalized CD8+ cytotoxic T lymphocytes (CTL) cells to attack tumor cells through the release of granozymes, granulysin, perforin, and Fas ligand (FasL) through Fas death receptor binding to cancer cells for apoptosis to occur." (PMID 37513835, 2023). "It has been shown that Fas ligand (FasL), highly expressed in tumor-associated ECs, selectively mediates CTL but not Treg apoptosis." (PMID 36523993, 2022).
tumor (continued). "The potential mechanism may be that IL-18 plays an important role in anti-tumor immunity through enhancing interferon-γ production and Fas ligand dependent cytotoxicity of immune cells, and the dose of IL-18 was correlated with the level of serum IFN-γ." (PMID 35865545, 2022). "The upregulation of FAS ligand (FAS-L) on endothelial cells could have the final effect of T-lymphocyte death and could promote tumor growth and immunosuppression, blocking cytotoxic T-lymphocyte activation and maturation." (PMID 36290857, 2022). "In addition to the perforin-granzyme pathway, γδ T cells also kill tumor cells by expressing TNF-related apoptosis-inducing ligand (TRAIL) and Fas ligand (FasL), which engage their respective receptors expressed by tumor cells to induce apoptosis." (PMID 35740670, 2022). "In addition, CAR-NK cells can lyse tumor cells directly by releasing cytoplasmic granules containing perforin and granzyme or inducing tumor cell apoptosis by expression of Fas ligand or TNF-related apoptosis-inducing ligand (TRAIL)." (PMID 36353643, 2022). "In addition, miR-21 can modulate the external apoptotic pathway through suppression of FasL (Fas ligand), which is especially noticeable in tumor stem cells." (PMID 35330864, 2022). "Likewise, Tumor-derived exosomes (TEXs) regulate the process of tumor formation due to release of immunosuppressive molecules such as Fas-ligand (FasL), the expression of which contributes to resistance and malignant niche selection." (PMID 36032679, 2022). "The overexpression of FASLG simplifies the progression of the tumor." (PMID 35041720, 2022). "NK cells are a major effector cell of the innate immune system that can eliminate tumor cells either by degranulation (granzyme) or by expressing Fas Ligand (CD95L) or TRAIL on their surface which in turn interacts with DRs on the tumor cells to induce apoptosis." (PMID 36496977, 2022). "Additionally, in this dataset, there was a significantly higher expression of FASLG (GenBank AF288573) in healthy tissue compared to tumor tissue (FASLG control 4.56 ± 0.05, FASLG NSCLC 4.42 ± 0.04 [p = 0.0239])." (PMID 36359256, 2022). "Activated CD8+ T cells can kill tumor cells by perforating proteases of the Fas/Fas ligand pathway." (PMID 36105715, 2022). "Some studies have suggested that neutrophils may induce tumor cell apoptosis in vitro through the Fas/Fas ligand (FasL) pathway, which is an important cellular pathway involved in the regulation of apoptosis." (PMID 35884427, 2022). "EVs derived from NK cells exert tumor cell killing and inhibitory functions through four main mechanisms, including Fas/Fas ligand (FasL) pathway, perforin/granzyme pathway, tumor necrosis factor (TNF)-α pathway, and miRNA-mediated targeted regulation pathways." (PMID 35915054, 2022). "Since ADAM10 can enhance the anti-apoptotic ability of tumor cells by hydrolyzing Fas ligand." (PMID 35551177, 2022). "Activated TDLN B cells express Fas ligand, which is upregulated by co-culture with tumor cells." (PMID 35759090, 2022). "Fas-ligand is expressed by many tumors and is a means by which these tumors can engage Fas-receptor on NK- and/or T- cells and thereby initiate “suicide” of the effector lymphocytes and protection of the tumor cells." (PMID 35366943, 2022). "CD8+ T cells exert cytotoxic activity against tumor cells by triggering apoptotic cell death via granule exocytosis involving perforin and granzymes and via the death ligand/receptor system involving Fas ligand, TNF-α, and TNF-related apoptosis-inducing ligand." (PMID 35216272, 2022). "In addition, the overexpression of Fas (CD95) by T lymphocytes and the Fas ligand (FasL) by tumor cells induces the apoptosis of activated T cells." (PMID 35335881, 2022).